RNU6-539P (RNA, U6 small nuclear 539, pseudogene)
Gene: Small nuclear RNA gene on chromosome 14 (49,839,725 to 49,839,827, forward strand). Ensembl gene ENSG00000252474.
Homologues: Orthologues: macaque U6 (87% identical), mouse Gm22543 (79% identical). Paralogues in human: RNU6-144P (90% identical), RNU6-16P (90% identical), RNU6-25P (90% identical), RNU6-29P (90% identical), RNU6-38P (90% identical), RNU6-46P (90% identical), RNU6-1 (89% identical), RNU6-2 (89% identical), RNU6-20P (89% identical), RNU6-39P (89% identical), RNU6-3P (89% identical), RNU6-434P (89% identical), and 1285 more.